IER5 (immediate early response 5)
Diseases named in the same sentence as IER5 in open-access papers (continued):
Sharing a sentence is not in itself a finding about the gene and the disease.
ovarian carcinoma (1 paper, 2025). A malignant neoplasm originating from the surface ovarian epithelium. "Methods/Results: Here we show that Ier5 mRNA expression is higher in ovarian cancer cells (MOV, ID8G, and HM-1) compared to normal ovarian cells." (PMID 40002205, 2025). "In this study, we created a mouse model of ovarian cancer peritoneal metastasis to analyze the potential role of IER5." (PMID 40002205, 2025). "Further, using siRNA knockdown we have shown that IER5 is required for the proliferation and growth of ovarian cancer (HM-1 and MOV) cells." (PMID 40002205, 2025). "We also found that IER5 is overexpressed in various cancers, the highest of which was in ovarian cancer." (PMID 40002205, 2025). "Previously, we reported that ovarian cancer has the highest degree of IER5 overexpression among various cancer types." (PMID 40002205, 2025). "We also observed high expression of Ier5 gene expression in mouse ovarian cancer cells derived from OSE (MOV, ID8G, and HM-1 cells)." (PMID 40002205, 2025). "Furthermore, analysis of data from an ovarian cancer mouse model seeded by OSE or FTE showed that higher expression of Ier5 is observed in ovarian cancer cells of OSE origin, whereas higher expression of Ier5l and Ier2 is observed in those derived from FTE." (PMID 40002205, 2025). "Since IER5 also contributes to the survival and proliferation of cancer cells in suspension, we wanted to examine whether IER5 is also involved in the metastasis of ovarian cancer cells." (PMID 40002205, 2025). "To assess the impact of Ier5 knockdown on HSF1 target genes, we analyzed the expression of HSPs in HM-1 and MOV ovarian cancer cells following knockdown." (PMID 40002205, 2025). "We showed that both IER5 and HSF1 are essential for ovarian cancer cell proliferation in both adherent and suspension conditions." (PMID 40002205, 2025). "To further investigate the role of IER5 in ovarian carcinogenesis, we knocked down Ier5 expression in HM-1 and MOV cells, two ovarian cancer cell lines having higher Ier5 expression, and analyzed the impact on cell growth." (PMID 40002205, 2025). "We also found that the expression of various HSF1 target genes is dependent on both IER5 and HSF1 in ovarian cancer cells." (PMID 40002205, 2025). "We also observed downregulation of key HSPs including Hspa1a, Hspa1b, and Dnajb1 upon Ier5 knockdown in HM-1 and MOV ovarian cancer cells." (PMID 40002205, 2025). "Since we found significant elevation of Ier5 mRNA in an ovarian cancer mouse model derived from OSE, we then decided to focus on the function of Ier5 in ovarian cancer cells derived from OSE." (PMID 40002205, 2025). "We found that Ier5 expression is elevated in ovarian cancer derived from OSE but not FTE, whereas both Ier5l and Ier2 were upregulated in those from FTE but not OSE." (PMID 40002205, 2025).
pancreatic cancer (1 paper, 2014). "Importantly, both Egr-1 and Ier5 were recently identified as cachexia-associated genes upregulated in muscles of pancreatic cancer patients together with Foxo1." (PMID 25539728, 2014).
squamous carcinoma (1 paper, 2020). "Among direct Notch target genes are multiple DNA damage response genes, including IER5, which we show is required for Notch-induced differentiation of squamous carcinoma cells and TERT-immortalized keratinocytes." (PMID 32936072, 2020).
tauopathy (1 paper, 2023). Neurodegenerative disorders involving deposition of abnormal tau protein isoforms (tau proteins) in neurons and glial cells in the brain. "IER5 is an established regulator of molecular chaperone expression, and has been reported to mediate upregulation of chaperone proteins upon sleep deprivation, suggesting a link between proteostasis and sleep, both of which are disrupted in AD, and both of which promote tauopathy." (PMID 36972319, 2023). "Our data show IER5 is downregulated in PFC and upregulated in CB, in accord with the upregulation of chaperone targets and with tauopathy resistance of the CB." (PMID 36972319, 2023).
cancer (11 papers, 2014 to 2025). A tumor composed of atypical neoplastic, often pleomorphic cells that invade other tissues. "Previous studies have suggested that higher IER5 expression is associated with poor prognosis in patients with various cancer diagnoses." (PMID 40852688, 2025). "IER5 is one of the growth factor-inducible genes and is reported to be associated with the poor prognosis of cancer patients." (PMID 34204836, 2021). "The IER5 locus is associated with a so-called super enhancer, frequently associated with hyperactivated oncogenes in cancer cell lines." (PMID 26754925, 2016). "We therefore analyzed the correlation between IER5 mRNA levels and the expression of cancer-associated HSF1 target genes in cancer patients." (PMID 26754925, 2016). "As we have shown, the IER5 gene is associated with super enhancers in cancers, indicating that it is a key gene involved in tumor pathogenesis." (PMID 26754925, 2016). "We have shown that IER5 expression is induced by growth stimuli, is overexpressed in various cancers, that the IER5 gene is associated with super-enhancers in cancer cells and that high IER5 expression is related to poorer prognosis of cancer patients." (PMID 26754925, 2016). "Basing on above studies, we speculate that high expression of IER5 is associated with adverse prognosis of cancer patients." (PMID 28430589, 2017). "This remarkably high incidence of super-enhancer association with the IER5 gene in cancer cell lines supports the idea that IER5 may be an important gene in tumor pathogenesis." (PMID 26754925, 2016). "Since enhanced IER5 expression is observed in many cancers, we asked whether the IER5 gene locus might also be associated with a super-enhancer in cancer cells." (PMID 26754925, 2016). "IER5 is known to generate a hypo-phosphorylated active form of HSF1 in various cancer cells, distinct from the canonical hyper-phosphorylated active form." (PMID 40002205, 2025). "IER5L is a member of the IER family that shares homology at its N-terminal domain with IER2 and IER5, which reportedly contribute to different aspects of cancer biology." (PMID 39025841, 2024). "Further, increased expression of IER5 has also been reported in several cancers, especially post-radio/chemotherapy." (PMID 37444509, 2023). "In the pan-cancer analysis, the results illustrated that the expression of IER5 were elevated in many kinds of tumors." (PMID 34222249, 2021). "We have shown that IER5 is required for the anchorage-independent growth of cancer cells and is an activator of HSF1." (PMID 26754925, 2016). "Enhanced expression of IER5 induces abnormal HSF1 activation in cancer cells and contributes to the proliferation of these cells under stressed conditions." (PMID 26754925, 2016). "Theses results show that HSF1 activation downstream of IER5 is important for proliferation of cancer cells." (PMID 26754925, 2016). "In order to analyze the function of IER5 in tumorigenesis, we examined the effect of IER5 expression on the growth of cancer cells." (PMID 26754925, 2016). "We next analyzed the effect of IER5 knockdown in four of the other cancer cell lines, and saw that IER5 had a significant effect on the growth in each line under suspension culture conditions." (PMID 26754925, 2016). "We would also like to clarify which transcription factors are involved in the upregulation of IER5 mRNA in cancer." (PMID 26754925, 2016). "HSF1 has been reported to be involved in stress-induced cancer cell proliferation via IER5." (PMID 36900163, 2023). "Previous investigations have reported the expression, as well as the functions of IER5 in cancers." (PMID 34222249, 2021). "We observe that depletion of IER5 in cancer cells results in decreased HSF1 activity." (PMID 26754925, 2016).
cancer (continued). "Furthermore, IER5-mediated activation of HSF1 is required for anchorage-independent cell growth of cancer cells." (PMID 26754925, 2016). "In addition, in cancer cells that exhibit enhanced IER5 expression, suppression of IER5 by siRNA results in the downregulation of HSF1 activity and cell proliferation." (PMID 26754925, 2016). "First, we analyzed the expression levels of IER5 in several cancer cell lines including cell lines identified as having or not having IER5-associated super enhancers: HCC1954, HeLa, MCF7, LNCaP, and HepG2." (PMID 26754925, 2016). "In addition, we also analyzed the expression of IER5 in cancer cell lines." (PMID 34222249, 2021). "Notably, IER5 as a member of the slow-kinetics class of immediate-early genes has demonstrated playing an essential role in nuclear response to extracellular signals, particularly with respect to radiation in diverse cancers." (PMID 28430589, 2017). "In addition, IER5 upregulation and overexpression has been observed in a number of cancers." (PMID 26754925, 2016). "Thus, IER5 appears to exert its function in a context-dependent manner involving its binding to various partners, but these diverse functions of IER5 may all contribute to stress resistance in both normal and cancer cells." (PMID 37444509, 2023). "We also have shown that mRNA expression of IER5 and HSF1 target genes show high correlation in several cancers." (PMID 26754925, 2016). "Finally, we showed that this IER5-HSF1-HSP axis is vital for cancer cell growth: Hsf1 knockdown resulted in reduced ovarian cancer cell (HM-1) proliferation and as well as decreased HSP expression, indicating that IER5 regulates HSPs via HSF1." (PMID 40002205, 2025). "The association of IER5 and HSPA6 expression with cancer progression may be related to the in vitro observation that IER5 and HSF1 are required for the proliferation of cancer cells under stressed conditions." (PMID 26754925, 2016). "IER5L levels consistently increased across cancer types (with a similar non-significant trend in PCa), while IER2 expression was largely reduced, and IER5 exhibited inconsistent alterations." (PMID 39025841, 2024). "In this manuscript, we have further shown that the IER5-mediated HSF1 activation can also occur in the absence of heat stress, and is highly important for proliferation of cancer cells." (PMID 26754925, 2016). "Unlike IER2 and IER5, the role of IER5L in cancer aggressiveness has been poorly studied." (PMID 39025841, 2024).
tumor (9 papers, 2013 to 2025). "IER5 mRNA protein and mRNA expression (in Western blot and qRT-PCR) was significantly associated with tumor size (p = 0.027 and p = 0.017)." (PMID 28430589, 2017). "Using an ANOVA model for repeated-measures, we found significant association between the IER5 level and tumor size (P < 0.05)." (PMID 28430589, 2017). "To analyze the association of IER family members (IER2, IER5 and IER5L) with tumor pathogenesis and progression, we interrogated public transcriptomics datasets containing gene expression data from different tumor types using Cancertool." (PMID 39025841, 2024). "GSEA showed that many tumor related pathways were enriched differentially in the IER5-high expression group." (PMID 34222249, 2021). "Another study found that the overexpression of IER5 promotes tumor cell anchorage-independent-growth under stress conditions through HSF1 activation." (PMID 34222249, 2021). "The results showed that there was remarkably higher expression of IER5 in tumor tissues in contrast with healthy tissues." (PMID 34222249, 2021). "Five of 6 probes (HIST1H1E, HIST1H4B, HIST1H4E, HIST4H4, 5960086) in the Normal dataset were also present in the analysis using all samples and 2 (HSPA1A, IER5) were in common in Tumor dataset." (PMID 23308215, 2013). "In contrast to the epithelial cells, carboplatin treatment led to increased expression of pro-survival factors (Bcl2, Mcl1, Ier3, Ier5, Hmox1) in stromal cell populations, thus preserving their viability and potentially providing a means of stabilizing and prolonging the anti-tumor response." (PMID 37660083, 2023). "Finally, we explored and discussed the possible mechanism between the expression of IER5 and the development of tumors by analyzing the relationship of IER5 expression with tumor immune infiltrates." (PMID 34222249, 2021). "In this report, we have mainly focused on the tumor-promoting functions of IER5." (PMID 26754925, 2016). "Interestingly, both IER2 and IER5 reportedly contribute to tumor progression." (PMID 39025841, 2024). "We also reported a two-fold higher expression of Ier5 in metastatic tumor cells (ID8-Om2 cells) compared to original tumor cells (ID8G), suggesting a role for IER5 in metastasis." (PMID 40002205, 2025). "We used Wilcoxon signed rank tests to analyze the expression level of IER5 in tumor and non-malignant tissues." (PMID 34222249, 2021). "Unlike IER2 and IER5, the role of IER5L has been poorly studied and thus, we lack basic understanding of the possible contribution of IER5L to tumor progression and metastasis." (PMID 39025841, 2024).
infection (2 papers, 2016 to 2020). The state of being infected such as from the introduction of a foreign agent such as serum, vaccine, antigenic substance or organism. "In the Kasumi-3 cells infected with NR-1, incubation with the miR-UL148D agomir also dampened the robust increase in IER5 expression observed during the early days (1–4 dpi) of infection." (PMID 27824944, 2016). "Infection with NR-1ΔmiR-UL148D, a derivative of the HCMV clinical strain NR-1 with a miR-UL148D knockout mutation, resulted in sustained induction of IER5 expression but decreased CDC25B expression in host cells." (PMID 27824944, 2016). "As shown, infection with LV-IER5 resulted in continuous high-level expression of IER5 in the NR-1-infected Kasumi-3 cells, even at late stages of infection, whereas CDC25B expression was significantly decreased along the 10-day time course." (PMID 27824944, 2016). "On the contrary, during the late stages of NR-1ΔmiR-UL148D infection, IER5 expression was maintained at a high level in infected cells, while CDC25B expression was virtually undetectable." (PMID 27824944, 2016). "During the early stages of NR-1 and NR-1ΔmiR-UL148D infection, IER5 expression in host cells rapidly increased, which was correlated with a decrease in CDC25B expression." (PMID 27824944, 2016). "As shown, possibly in response to HCMV early infection, the levels of IER5 in the Kasumi-3 cells and CD34+ HPCs infected with NR-1 or NR-1ΔmiR-UL148D were increased during the early days (1–4 dpi) of infection." (PMID 27824944, 2016). "In the Kasumi-3 cells infected with NR-1ΔmiR-UL148D, incubation with the miR-UL148D agomir strongly suppressed IER5 expression but restored CDC25B levels at late stages of infection." (PMID 27824944, 2016). "However, compared to 4 days post infection, IER5 levels in Kasumi-3 cells and CD34+ HPCs infected with NR-1 significantly decreased at later stages of infection (7–10 dpi), while levels of CDC25B expression were restored." (PMID 27824944, 2016). "In contrast, possibly due to the lack of miR-UL148D, both the Kasumi-3 cells and the CD34+ HPCs that were infected with NR-1ΔmiR-UL148D failed to suppress IER5 expression at later stages of infection, leading to sustained inhibition of CDC25B." (PMID 27824944, 2016).
neurological disease (1 paper, 2020). "The immediate‐early response gene 5, also known as Ier5, has been previously studied for its role in inflammation within neurological disease‐related gene studies." (PMID 32189431, 2020).
IER5 also shares sentences with these, for which no sentence is quoted: anemia (1 paper); astrocytoma (1); blood cancer (1); COVID-19 (1); glioblastoma (1); hepatocellular carcinoma (1); liver cancer (1); melanoma (1); non-small cell lung carcinoma (1); oligoastrocytoma (1); oligodendroglioma (1); prostate carcinoma (1); Sepsis (1).